ANAPC11 (anaphase promoting complex subunit 11)
Description:
Component of the anaphase promoting complex/cyclosome (APC/C), a cell cycle-regulated E3 ubiquitin ligase that controls progression through the cell cycle. Together with ANAPC2, forms the catalytic component of the E3 ubiquitin ligase complex. APC/C acts by mediating ubiquitination and subsequent degradation of target proteins: it mainly mediates the formation of 'Lys-11'-linked polyubiquitin chains and, to a lower extent, the formation of 'Lys-48'- and 'Lys-63'-linked polyubiquitin chains. APC/C catalyzes assembly of branched 'Lys-11'-/'Lys-48'-linked branched ubiquitin chains on target proteins. APC/C is activated by CDC20 in the metaphase/anaphase transition of cell cycle, targeting the degradation of cyclin B and securin. APC/C is regulated by the mitotic checkpoint complex (MCC), which inhibits APC/C and delays chromosome segregation.
Synonyms: APC11; HSPC214; Apc11p; MGC882
Tractability: PROTAC: UniProt records ubiquitination sites on it; ubiquitination databases record sites on it.
Gene: Protein-coding gene on chromosome 17 (81,890,669 to 81,900,991, forward strand). Ensembl gene ENSG00000141552.
Subcellular location: Cytoplasm; Nucleus
Subcellular location (Human Protein Atlas): Nucleoplasm; Nucleoli
Pathways (Reactome):
Cell Cycle: APC-Cdc20 mediated degradation of Nek2A; APC/C:Cdc20 mediated degradation of Cyclin B; APC/C:Cdc20 mediated degradation of Securin; APC/C:Cdc20 mediated degradation of mitotic proteins; APC/C:Cdh1 mediated degradation of Cdc20 and other APC/C:Cdh1 targeted proteins in late mitosis/early G1; Autodegradation of Cdh1 by Cdh1:APC/C; Cdc20:Phospho-APC/C mediated degradation of Cyclin A; Conversion from APC/C:Cdc20 to APC/C:Cdh1 in late anaphase; Inactivation of APC/C via direct inhibition of the APC/C complex; Phosphorylation of the APC/C; Regulation of APC/C activators between G1/S and early anaphase; Separation of Sister Chromatids
DNA Replication: Assembly of the pre-replicative complex; CDK-mediated phosphorylation and removal of Cdc6
Cellular responses to stimuli: Senescence-Associated Secretory Phenotype (SASP)
Disease: Aberrant regulation of mitotic exit in cancer due to RB1 defects
Gene expression (Transcription): Transcriptional Regulation by VENTX
Immune System: Antigen processing: Ubiquitination & Proteasome degradation
Gene Ontology:
Molecular function: cullin family protein binding; protein binding; ubiquitin protein ligase activity; ubiquitin-protein transferase activity; ubiquitin-ubiquitin ligase activity; G protein-coupled receptor binding; zinc ion binding
Biological process: anaphase-promoting complex-dependent catabolic process; positive regulation of mitotic metaphase/anaphase transition; protein branched polyubiquitination; protein K11-linked ubiquitination; protein K48-linked ubiquitination; protein ubiquitination; mitotic cell cycle; regulation of meiotic cell cycle; regulation of mitotic cell cycle; ubiquitin-dependent protein catabolic process; proteasome-mediated ubiquitin-dependent protein catabolic process
Cellular component: anaphase-promoting complex; nucleolus; nucleoplasm; cytosol; nucleus; cullin-RING ubiquitin ligase complex; cytoplasm
Genetic constraint (gnomAD): Loss-of-function variants: 4 observed, 11.65 expected, observed/expected ratio (o/e) 0.34, 90% interval 0.17 to 0.79. The upper end of that interval is the gene's LOEUF score, 0.79, which puts it in group 3 of 6, group 1 being the genes least tolerant of losing a copy. Missense variants: 68 observed, 117.1 expected, observed/expected ratio (o/e) 0.58, 90% interval 0.48 to 0.71. Synonymous variants: 45 observed, 40.41 expected, observed/expected ratio (o/e) 1.11, 90% interval 0.88 to 1.43.
Homologues: Orthologues: dog ANAPC11 (99% identical), guinea pig ANAPC11 (99% identical), mouse Anapc11 (99% identical), rat Anapc11 (99% identical), zebrafish anapc11 (92% identical), rabbit ANAPC11 (88% identical), tropical clawed frog anapc11 (88% identical), Drosophila melanogaster lmgA (71% identical), Caenorhabditis elegans apc-11 (50% identical). Paralogues in human: RBX1 (39% identical), RNF7 (37% identical).
Diseases named in the same sentence as ANAPC11 in open-access papers:
ANAPC11 is named in the same sentence as 21 diseases in open-access papers, as found by Europe PMC text mining. Sharing a sentence is not in itself a finding about the gene and the disease. The quoted sentences say what the papers report.
colorectal cancer (2 papers, 2018 to 2020). A primary or metastatic malignant neoplasm that affects the colon or rectum. "Likewise, aberrant increases of APC10 and APC11 proteins, which are two subunits of the APC/C encoded by ANAPC10 and ANAPC11 genes, have been recently evidenced in non-small cell lung and colorectal cancer tissues; interestingly, inhibitors of APC/C activity are currently under investigation." (PMID 33585202, 2020).
inflammatory bowel disease (1 paper, 2022). A spectrum of small and large bowel inflammatory diseases of unknown etiology. "ANAPC11 is anaphase promoting complex subunit 11 and, to the best of our knowledge, was never before mentioned in relation to inflammatory bowel disease or anti-TNF response." (PMID 36145641, 2022).
ischemic heart disease (1 paper, 2021). "Results also support the ontology bioinformatics evidence that CTB89H12.4/miR-137/FTHL-17 and CTB89H12.4/miR-106b-5p/ANAPC11 networks synergistically regulate the Nourin protein expression in myocardial ischemia, and thus provide a novel molecular mechanism in ischemic heart disease." (PMID 33670982, 2021).
liver cancer (1 paper, 2023). An epithelial or non-epithelial malignant neoplasm that arises from the liver. "For instance, lncRNA BCAR4 may promote the proliferation, migration, and invasion of liver cancer cells by directly binding to miR-1261 and targeting the anaphase-promoting complex subunit 11 (ANAPC11) gene." (PMID 36851037, 2023).
malaria (1 paper, 2022). Malaria is a serious and sometimes fatal disease caused by a parasite that commonly infects a certain type of mosquito which feeds on humans. "ANAPC11 is a ubiquitination process gene and is associated with dysregulation in innate immunity in malaria." (PMID 36145641, 2022).
myocardial ischemia (1 paper, 2021). A disorder of cardiac function caused by insufficient blood flow to the muscle tissue of the heart. "The downregulation of CTB89H12.4 after myocardial ischemia results in an increase in the expression of miR-137 and miR-106b-5p, which sequentially activates the FTHL-17 and ANAPC11, respectively, with an increased translation and production of Nourin protein." (PMID 33670982, 2021).
urothelial carcinoma (1 paper, 2023). A malignant neoplasm derived from the transitional epithelium of the urinary tract (urinary bladder, ureter, urethra, or renal pelvis). "In the present study, we revealed a novel mechanism by which the APC/C catalytic subunit ANAPC11 promotes urothelial carcinoma cell proliferation and LN metastasis." (PMID 37573356, 2023). "Thus, in the present study, we elucidated the mechanisms by which ANAPC11 governs FOXO3 protein degradation to promote urothelial carcinoma cell proliferation and LN metastasis." (PMID 37573356, 2023).
tumor (6 papers, 2011 to 2026). "ANAPC11, commonly up-regulated, appears to be a very important factor in the regulation of cell cycle progression, whereas its aberrant expression is linked to tumor progression." (PMID 21483740, 2011). "The expression of ANAPC11 was detected in tumor sections by IHC staining, and knockout of ANAPC11 was found to induce increased expression of FOXO3, p21, and GULP1 and decreased expression of Ki67, a well-known marker for cell proliferation." (PMID 37573356, 2023).
ANAPC11 also shares sentences with these, for which no sentence is quoted: cancer (5 papers); pancreatic carcinoma (2); adenoma (1); breast carcinoma (1); cervical carcinoma (1); colon cancer (1); colorectal tumors (1); hepatocellular carcinoma (1); melanoma (1); metastatic tumors (1); non-small cell lung carcinoma (1); pancreatic adenocarcinoma (1); urothelial bladder cancer (1).